LAMA2 (laminin subunit alpha 2)
Diseases named in the same sentence as LAMA2 in open-access papers (continued):
Sharing a sentence is not in itself a finding about the gene and the disease.
congenital muscular dystrophy (continued). "Mutations in the LAMA2 gene encoding laminin α2 chain cause congenital muscular dystrophy with laminin α2 chain-deficiency (LAMA2-CMD), a very severe muscle disorder." (PMID 30389963, 2018). "For example patient WES32 presented with adult onset proximal weakness with CK >1000 iu/L and was therefore considered to have an LGMD, but actually had disease due to LAMA2 mutations, more usually associated with congenital muscular dystrophy." (PMID 28877744, 2017). "Laminin-deficient congenital muscular dystrophy (LAMA2-CMD) is a severe form of congenital muscular dystrophy caused by mutations in the gene encoding laminin α2 chain." (PMID 28771630, 2017). "A mouse model for congenital muscular dystrophy caused by Lama2 deficiency can be treated effectively by injecting recombinant Laminin1-1-1 trimer." (PMID 24941943, 2014). "Mutations in the LAMA2 gene, encoding the α2 chain of laminin-2, cause α 2-laminin deficiency and a severe form of congenital muscular dystrophy (CMD1A) linked to chromosome 6q." (PMID 25221510, 2014). "Laminin α2 (LAMA2)-deficient congenital muscular dystrophy is a severe, early-onset disease caused by abnormal levels of laminin 211 in the basal lamina leading to muscle weakness, transient inflammation, muscle degeneration and impaired mobility." (PMID 21850221, 2011). "Mutations in LAMA2 gene are known to be involved in the MDC1A form representing that which is most frequent in cases of congenital muscular dystrophy." (PMID 21637626, 2010). "The mutation of LAMA2, a gene encoding laminin-α2, can lead to congenital muscular dystrophy." (PMID 38504181, 2024). "Mutations in LAMA2 trigger the often-lethal LAMA2-congenital muscular dystrophy (LAMA2-CMD)." (PMID 39379105, 2024). "LAMA2 gene mutations have been shown to cause congenital muscular dystrophy in dogs and mice." (PMID 38473080, 2024). "LAMA2 is primarily associated with congenital muscular dystrophies (CMD)." (PMID 38046810, 2023). "Mutations of LAMA2 gene are associated with congenital muscular dystrophy (CMD)." (PMID 37404563, 2023). "Congenital muscular dystrophy associated with a disease variant in LAMA2 was identified." (PMID 34854126, 2021). "The research on laminin α2 chain-deficient congenital muscular dystrophy (LAMA2-CMD) advanced rapidly in the last few decades, largely due to availability of good mouse models for the disease and a strong interest in preclinical studies from scientists all over the world." (PMID 32457577, 2020). "Other researchers have shown that macrocephaly occurs in conjunction with congenital muscular dystrophy due to mutation of gene laminin subunit alpha 2, multifocal demyelinating motor neuropathy and Hamartoma syndrome associated with a ‘de novo’ mutation in the phosphatase and tensin homolog gene." (PMID 33233862, 2020). "Lama2-linked muscular dystrophy is a serious congenital muscular dystrophy produced by mutations in the LAMA2 gene, and is associated with several pathological problems such as inflammation, apoptosis, fibrosis, necrosis, severe muscle weakness, and subnominal postnatal growth." (PMID 32722232, 2020). "Second, laminins with a LAMA2 encoded chain are found in the basal lamina of basement membranes; the chain is also related to cartilage development and has been implicated in congenital muscular dystrophy." (PMID 24498183, 2014). "Lama2-/- mice are a model for the severely disabling human disease, primary laminin-α2-deficient Congenital Muscular Dystrophy Type 1A, which is also known as merosin-deficient congenital muscular dystrophy." (PMID 15817132, 2005). "LAMA2-deficient congenital muscular dystrophy (LAMA2-CMD) is a severe neuromuscular disorder characterized by muscle degeneration, chronic inflammation, and fibrosis." (PMID 40161708, 2025). "Congenital muscular dystrophy (CMD) is a progressive dystrophy caused by mutations in LAMA2 encoding the laminin α2 chain which is necessary for laminin 211 formation (see chapter 4)." (PMID 40688418, 2025).
congenital muscular dystrophy (continued). "Laminin-α2-related congenital muscular dystrophy (LAMA2-CMD) is a devastating neuromuscular disease caused by mutations in the LAMA2 gene." (PMID 32116540, 2020). "Laminin-α2-related congenital muscular dystrophy (LAMA2-CMD), also known as merosin deficient congenital muscular dystrophy type 1A (MDC1A), is a genetic disease caused by mutations in the LAMA2 gene encoding the laminin-α2 protein." (PMID 32116540, 2020). "LAMA2-related congenital muscular dystrophy (CMD; LAMA2-MD), also referred to as merosin deficient CMD (MDC1A), is a severe neonatal onset muscle disease caused by recessive mutations in the LAMA2 gene." (PMID 32742259, 2020). "Laminin-α2-related congenital muscular dystrophy (LAMA2-CMD) is a devastating genetic disease caused by mutations in the LAMA2 gene." (PMID 32498713, 2020). "Laminin-α2 chain (merosin) deficient congenital muscular dystrophy 1A (MDC1A) is the most prevalent form of CMD, caused by mutations in the LAMA2 gene." (PMID 29763467, 2018). "Merosin-deficient CMD type 1A (MDC1A), caused by mutations of laminin subunit alpha 2 (LAMA2), is a predominant subtype of congenital muscular dystrophy (CMD)." (PMID 29487616, 2018). "LAMA2-MD has an estimated prevalence of 4 in 500,000 children, and accounts for 36–48% of patients with congenital muscular dystrophies (CMDs)." (PMID 40960171, 2025). "Cockayne syndrome accounted for 20.9% (18/86) and LAMA2-related congenital muscular dystrophy (LAMA2-CMD) for 12.8% (11/86), representing significant categories." (PMID 40514726, 2025). "LAMA2-RD can present with a wide range of phenotypes ranging from severe infantile congenital muscular dystrophy to milder adult-onset limb-girdle muscular dystrophy." (PMID 38975466, 2024). "Two clinical phenotypes of LAMA2-MD have been identified: early-onset LAMA2 related congenital muscular dystrophy (LAMA2-CMD, also known as congenital muscular dystrophy type 1A, MDC1A) and mild, late-onset limb girdle muscular dystrophy (LGMD R23)." (PMID 37206914, 2023). "LAMA2-CMD is a severe form of congenital muscular dystrophy characterized by hypotonia, progressive muscle weakness and respiratory insufficiency." (PMID 37021539, 2023). "Mutations in LAMA2 lead to a congenital muscular dystrophy (LAMA2-CMD; also known as merosin-deficient congenital muscular dystrophy type 1A, MDC1A) which is characterized by muscle weakness, fibrosis, and chronic inflammation." (PMID 34394183, 2021). "LAMA2-CMD is one of the most common congenital muscular dystrophies (CMDs) in the world, accounting for 36.4%-48% of CMD patients." (PMID 34281576, 2021). "Investigators from the NIH performed a longitudinal, prospective, natural history study looking at patients with COL6-related dystrophies (COL6-RDs) and LAMA2-related dystrophies (LAMA2-RDs), the two most common congenital muscular dystrophies (CMDs)." (PMID 33304089, 2020). "Seven patients had congenital muscular dystrophies: LAMA2-related dystrophy (n = 5), COL6-related dystrophies (n = 1) or α-dystroglycanopathy (n = 1), and three patients had congenital myopathies: DNM2-related myopathy (n = 1) and TTN-related myopathy (n = 2)." (PMID 32028919, 2020). "Laminin α2 gene (LAMA2)-related Congenital Muscular Dystrophy (CMD) was distinguished by a defining central nervous system (CNS) abnormality—aberrant white matter signals by MRI—when first described in the 1990s." (PMID 32792907, 2020). "The spectrum of muscular dystrophies in dogs has also expanded in recent years to include forms of limb–girdle muscular dystrophy associated with variants in sarcoglycan genes (SGCD and SGCA) and congenital muscular dystrophies with variants identified in the COL6, LAMA2, and LARGE1 genes." (PMID 37628610, 2023). "Mutations in the LAMA2 gene that result in either absent or defective laminin α2 subunits cause an autosomal recessive congenital muscular dystrophy." (PMID 35639486, 2022).
congenital muscular dystrophy (continued). "LAMA2 deficiency, resulting from a defective or absent laminin α2 subunit, is a common cause of congenital muscular dystrophy." (PMID 35639486, 2022). "Mutations of LAMA2 and LAMB2 cause congenital muscular dystrophy (muscle atrophy) in embryos." (PMID 33809502, 2021). "To investigate if recombinant human laminin-111 could prevent disease progression, we generated an immunodeficient dyW mouse model of laminin-α2-related congenital muscular dystrophy (LAMA2-CMD)." (PMID 32498713, 2020). "Congenital muscular dystrophy with laminin α2 chain-deficiency (LAMA2-CMD) is a severe neuromuscular disorder without a cure." (PMID 32197453, 2020). "Laminin-α2-related congenital muscular dystrophy (LAMA2-CMD) is a neuromuscular disease affecting around 1-9 in 1,000,000 children." (PMID 37021539, 2023). "The clinical spectrum ranges from a severe, early-onset LAMA2-related congenital muscular dystrophy (LAMA2-CMD, OMIM 607,855) to a mild, childhood-onset autosomal recessive limb-girdle muscular dystrophy-23 (LGMDR23, OMIM 618,138)." (PMID 34281576, 2021). "In the past 25 years, researchers and clinicians have expanded our knowledge of brain involvement in LAMA2-related CMD, also known as Congenital Muscular Dystrophy Type 1A (MDC1A)." (PMID 32792907, 2020). "Despite significant development of successful genetic and pharmacological preclinical treatment strategies in mice there is still no cure for LAMA2-CMD, the second-most common form of congenital muscular dystrophy." (PMID 32197453, 2020). "Although several treatment approaches have been shown to improve muscle histopathology in mouse models of LAMA2-CMD, only one clinical trial has been performed for this congenital muscular dystrophy." (PMID 37021539, 2023). "Examples of loss of function in ECM components could be observed in laminin α2-related congenital muscular dystrophy (LAMA2-CMD) and collagen VI myopathies." (PMID 34884495, 2021). "LAMA2-CMD, the second-most common form of congenital muscular dystrophy, remains incurable despite the development of successful genetic and pharmacological preclinical treatment strategies." (PMID 30389963, 2018).
Congenital muscular dystrophy type 1A (33 papers, 2011 to 2025). "LAMA2 variants are associated with congenital muscular dystrophy type 1A (MDC1A), a condition characterized by severe motor weakness within the first six months of life." (PMID 37107589, 2023). "Congenital muscular dystrophy type 1A (MDC1A) is caused by mutations in LAMA2 encoding the laminin α2 chain." (PMID 36312227, 2022). "In congenital muscular dystrophy type 1A (LAMA2-CMD), mutations in Lama2 gene cause either complete or partial absence in laminin-211 protein." (PMID 32523512, 2020). "LAMA2 is a methylation target in CRC with mutations predisposing to congenital muscular dystrophy type 1A (MCD1A)." (PMID 29212164, 2017). "Mutations in the LAMA2 gene, encoding the laminin α2 chain of the extracellular matrix protein laminin-211, leads to congenital muscular dystrophy type 1A (MDC1A), which is a life threatening disease." (PMID 26731667, 2016). "Congenital muscular dystrophy type 1A (MDC1A) is an autosomal recessive neuromuscular disorder caused by mutations in the LAMA2 gene encoding the laminin α2 chain a component of the skeletal muscle extracellular matrix protein laminin-211." (PMID 22166137, 2011). "Congenital muscular dystrophy type 1A is caused by mutations in the LAMA2 gene that encodes the laminin α2 chain, a component of the skeletal muscle extracellular matrix protein laminin-211." (PMID 22166137, 2011). "Mutations in LAMA2 encoding laminin α2 cause muscular dystrophy congenital type 1A." (PMID 35990309, 2022). "Muscular dystrophy congenital type 1A (MDC1A) is caused by mutations in LAMA2 encoding laminin α2." (PMID 35990309, 2022). "Congenital muscular dystrophy type 1A (MDC1A) is an autosomal recessive disorder caused by variants in the laminin alpha 2 chain gene (LAMA2)." (PMID 41567540, 2025). "Congenital muscular dystrophy type 1A (CMD1A) is a rare autosomal recessive disorder caused by mutations in the LAMA2 gene." (PMID 37415604, 2023). "Congenital muscular dystrophy type 1A (MDC1A) is a severe muscle disorder caused by mutations in the LAMA2 gene." (PMID 28367954, 2017). "Congenital muscular dystrophy type 1A (MDC1A) is an autosomal recessive disorder caused by mutations in the human LAMA2 gene, encoding the α2 subunit of laminin-2118." (PMID 28367954, 2017). "Mutations in the human LAMA2 gene, encoding the laminin α2 chain, lead to congenital muscular dystrophy type 1A (MDC1A)." (PMID 25071564, 2014). "A further example of this approach is the treatment of congenital muscular dystrophy type 1A (MDC1A), an autosomal recessive disorder resulting from mutations in both copies of the LAMA2 gene." (PMID 40650152, 2025). "Loss of its ±2 subunit encoded by the LAMA2 gene causes merosin-deficient congenital muscular dystrophy (MDCA1), or congenital muscular dystrophy type 1A." (PMID 34298968, 2021). "Congenital muscular dystrophy Type 1A (MDC1A) is a severe, recessive disease of childhood onset that is caused by mutations in the LAMA2 gene encoding laminin-α2." (PMID 24314268, 2013). "Congenital muscular dystrophy type 1A (LAMA2-CMD), also known as merosin-deficient congenital muscular dystrophy type 1A (MDC1A), is a devastating incurable disease, caused by mutations in Lama2 gene encoding the α-subunit of laminin-211." (PMID 32523512, 2020). "Such variants are associated with the complete absence of laminin-α2 protein in muscle biopsies and correlate with the congenital muscular dystrophy type 1A (MDC1A) phenotype—the severe, early-onset form of LAMA2-related disease." (PMID 41567540, 2025). "Laminin-a2-related muscular dystrophy (LAMA2-MD) has a similar clinical phenotype, which ranges from severe, early-onset congenital muscular dystrophy type 1A (MDC1A) to milder forms presenting as childhood- or adult-onset limb-girdle type muscular dystrophy." (PMID 39443859, 2024).
Congenital muscular dystrophy type 1A (continued). "LAMA2-MD has a disease spectrum ranging from severe, early-onset congenital muscular dystrophy type 1A (MDC1A), to a milder childhood- or adult-onset limb-girdle-type muscular dystrophy." (PMID 39443859, 2024). "For example, congenital muscular dystrophy type 1A (MDC1A) is an autosomal recessive disorder caused by mutations in LAMA2 that cause production of nonfunctional laminin-α2." (PMID 32106616, 2020). "Depending on the extent of laminin-α2 deficiency, the clinical manifestations of LAMA2 related muscular dystrophy (LAMA2-MD) range from severe congenital muscular dystrophy type 1A (MDC1A, OMIM#607855) to milder late-onset LAMA2-MD (OMIM#618138)." (PMID 37388928, 2023).
breast cancer (12 papers, 2014 to 2024). A primary or metastatic malignant neoplasm involving the breast. "LAMA2 mutations or expression aberrations, as for other stromal genes, has been repeatedly shown to be associated with a poorer prognosis in breast cancer." (PMID 33722295, 2021). "In laryngeal squamous cell carcinoma and breast cancer, downregulation of Lama2 expression was linked to tumor progression." (PMID 34305583, 2021). "In brain metastases of breast cancer, there was a loss of LAMA2, which correlated with an increase in BTB permeability." (PMID 31695842, 2019). "LAMA2 and TIMP4 were significantly associated and TMTC1 gene was less correlated with breast cancer occurrence." (PMID 37238942, 2023). "LAMA2 and TIMP4 were found significantly associated and TMTC1 gene was found less correlated with breast cancer occurrence." (PMID 37238942, 2023). "We found that LAMA2 and TIMP4 were significantly associated and TMTC1 gene was less correlated with breast cancer occurrence." (PMID 37238942, 2023). "LAMA2 and TIMP4 were found significantly associated and TMTC1 was found less correlated with breast cancer occurrence." (PMID 37238942, 2023). "Accordingly, downregulation of LAMA2 expression was connected to tumor progression in other tumor types like laryngeal squamous cell carcinoma and breast cancer." (PMID 25159915, 2014). "We identified 7 genes (ITGB1, SNAI1, NOTCH4, STAT5B, RAPGEF3, LAMA2, and GNAI1) that have been implicated in both stemness and the drug response and validated their relevance through an analysis of data from breast cancer patients in the TCGA database using UCSC Xena." (PMID 39180549, 2024). "However, suppression of LAMA2 expression could promote the invasiveness of breast cancer cells, and low expression level of LAMA2 predicted poor survival and higher recurrence rate in patients with hepatocellular carcinoma." (PMID 37519798, 2023). "OncoLnc was used to analyze the effect of expression levels of LAMA2, TIMP4, and TMTC1 on the survival of breast cancer patients." (PMID 37238942, 2023). "OncoLnc was used to analyse the effect of expression levels of LAMA2, TIMP4, and TMTC1 on the survival of breast cancer patients." (PMID 37238942, 2023). "The genes namely COL11A1, MMP11 and COL10A1 were found up-regulated and PCOLCE2, LAMA2, TMTC1, and TIMP4 were found down-regulated in breast cancer cell lines also." (PMID 37238942, 2023). "Among these key genes COL11A1, MMP11 and COL10A1 were highly expressed and PCOLCE2, LAMA2, TMTC1, ADAMTS5, TIMP4, and RSPO3 were having lower expression levels in breast cancer samples." (PMID 37238942, 2023). "Expression level of LAMA2, TIMP4, and TMTC1 was higher in all different stages of TCGA breast cancer samples and significantly expressed among different age groups of patients (younger to older age group)." (PMID 37238942, 2023). "In conclusion, our study identified nine key regulators, of which COL11A1, MMP11 and COL10A1 were up regulated and PCOLCE2, LAMA2, TMTC1, ADAMTS5, TIMP4 and RSPO3 were down regulated in breast cancer samples as compared to control samples." (PMID 37238942, 2023). "The genes namely COL11A1, MMP11 and COL10A1 were found up regulated and PCOLCE2, LAMA2, TMTC1, ADAMTS5, TIMP4 and RSPO3 were found down regulated in breast cancer." (PMID 37238942, 2023). "We have previously examined three laminin subunit genes (LAMA1, LAMA2, and LAMB1), the promoter regions of which undergo abnormal methylation in breast cancer (BC) at frequencies higher than 16%5." (PMID 33500458, 2021). "Moreover, we further deeply investigated the role of LAMA2, TMTC1 and TIMP4 genes in breast cancer prognosis." (PMID 37238942, 2023).
limb-girdle muscular dystrophy (12 papers, 2020 to 2025). Limb-girdle muscular dystrophy (LGMD) is a heterogeneous group of muscular dystrophies characterized by proximal weakness affecting the pelvic and shoulder girdles. "Here, we describe a relatively large cohort of Chinese patients carrying homozygous or compound heterozygous mutations of LAMA2 who manifest a limb girdle muscular dystrophy phenotype." (PMID 37206914, 2023). "The laminin α2 (LAMA2) gene pathogenic variants can lead to limb-girdle muscular dystrophy (known as LGMDR23), which is rarely reported and characterized by proximal weakness in the limbs." (PMID 36860576, 2023). "However, studies conducted in the United Kingdom and Denmark indicate that pathogenic or likely pathogenic variants in LAMA2 were identified in 2–3% of patients with limb-girdle muscular dystrophy." (PMID 39941024, 2025). "LAMA2-related limb girdle muscular dystrophy (LGMD R23) is rare." (PMID 37206914, 2023). "Muscle eosinophilia has been reported in several neuromuscular diseases including Duchenne and Becker Muscular Dystrophy, LAMA2-CMD muscular dystrophy, Limb-girdle muscular dystrophy, and idiopathic eosinophilic myositis." (PMID 38340007, 2024).